MEG3 (maternally expressed 3)
Diseases named in the same sentence as MEG3 in open-access papers (continued):
Sharing a sentence is not in itself a finding about the gene and the disease.
esophageal squamous cell carcinoma (12 papers, 2018 to 2025). Esophageal squamous cell carcinoma (ESCC) is a type of esophageal carcinoma (EC) that can affect any part of the esophagus, but is usually located in the upper or middle third. "Furthermore, MEG3 downregulation has been linked to poor prognosis in patients with esophageal SCC." (PMID 34140005, 2021). "The predicted top five lncRNAs are MALAT1, MEG3, BCYRN1, UCA1, and LSINCT5, among which MALAT1 and MEG3 are found to be associated with esophageal squamous-cell carcinoma in lncRNADisease in 2017." (PMID 35186029, 2022). "MEG3 downregulation has been noted in esophageal SCC cells, EC cells and tissues, all of which was consistent with our data." (PMID 34140005, 2021). "In esophageal squamous cell carcinoma, hypermethylation of the MEG3 promoter has been observed, which is related to the downregulation of MEG3, and after treatment with the DNA methyltransferase inhibitor 5-Aza-dC, this process can be reversed." (PMID 33828990, 2021). "Notably, ectopic expression of MEG3 has demonstrated the ability to significantly inhibit the proliferation, migration, invasion, and EMT of esophageal squamous cell carcinoma (ESCC) cells by down-regulating PSAT1 expression." (PMID 38706897, 2024). "Overexpression of LncRNA maternally expressed gene 3 (MEG3) could downregulate PSAT1 and suppress the activation of GSK-3β/Snail signaling pathway in esophageal squamous cell carcinoma (ESCC)." (PMID 37127605, 2023). "Interestingly, lncRNA MEG3 exerts tumor-suppressive effects and inhibits Epithelial-mesenchymal transition (EMT) by suppressing the PSAT1-dependent GSK3β/Snail signaling pathway in esophageal squamous cell carcinoma (ESCC)." (PMID 37147729, 2023).
ischemia (12 papers, 2017 to 2024). A hypoperfusion of the BLOOD through an organ or tissue caused by a PATHOLOGIC CONSTRICTION or obstruction of its BLOOD VESSELS, or an absence of BLOOD CIRCULATION. "It was reported that physically MEG3 was linked with miR-21, and miR-21 was downregulated following ischemia, which was opposite to MEG3." (PMID 31660855, 2019). "Here, we report that MEG3 is physically associated with microRNA-21 (miR-21), while miR-21 is downregulated following ischemia in the ischemic core in vitro and in vivo, which is opposite to MEG3." (PMID 29238035, 2017). "We found MEG3 was physically associated with miR-21, while miR-21 was downregulated following ischemia in the ischemic core in vitro and in vivo." (PMID 29238035, 2017). "Moreover, given the relevant role played by inflammation in the testes of our patients, it was i intriguing that, recently, MEG3 was found to promote pyroptosis, i.e., a form of cell-death associated with inflammatory signals, in testicular ischemia-reperfusion (IR) injury." (PMID 36147743, 2022). "However, the mechanisms underlying the effects of MEG3 in ischemia are not well understood." (PMID 29238035, 2017). "MEG3 was upregulated in cerebral infarction area, and MEG3 knockdown vector was transfected into the striatum of ischemia/reperfusion rat, which reduced infarct size and promoted angiogenesis." (PMID 33613191, 2020). "Silencing of MEG3 resulted in a proangiogenic effect through upregulation of Notch pathway-related genes in both ischemia brains and endothelial cells, leading to enhanced functional recovery and reducing the focal ischemia volume after a stroke." (PMID 32241300, 2020). "A recent study showed that the expression of lncRNA MEG3 was significantly upregulated following ischemia in vitro and in vivo, and it mediates ischemic neuronal death by targeting the miR-21/PDCD4 signaling pathway." (PMID 33192490, 2020). "And what’s more, si-MEG3 treatment markedly improved long-term learning and memory deficits, locomotor activity and anxiety-like behavior post-ischemia." (PMID 29238035, 2017). "However, other lncRNAs, such as Meg3, Malat1, GAS5, NEAT1, and LOC105374325 mediated the renal cell apoptosis caused by ischemia." (PMID 36552750, 2022). "As it has been proved that lncRNA and miRNA interact with each other in various diseases including several tumors and ischemic disorders, we further hypothesized that MEG3 function as a ceRNA competitively binding to miRNAs in the development of ischemia." (PMID 32065781, 2020). "Thus, the increased expression of MEG3 in ischemia highlights its role as an emerging target in the treatment of ischemia." (PMID 29238035, 2017). "Although here we described that MEG3 competed with PDCD4 mRNA for binding to miR-21 in ischemia, we didn’t exclude the possibility of other targets of MEG3 or miR-21 which may also contribute to the ischemic neuronal death." (PMID 29238035, 2017). "However, less is known regarding the biology and function of MEG3 in ischemia." (PMID 29238035, 2017). "In contrast to the consistently upregulation of MEG3 following ischemia (middle), miR-21 was abruptly decreased at 24 h of reperfusion, and then downregulated at a much slower pace at 48 h and 72 h in the ischemic core, indicating its potential role in ischemia (right)." (PMID 29238035, 2017). "However, although the relationship of MEG3 expression with a variety of tumors has been confirmed, MEG3 have not been functionally characterized in ischemia, thus, the mechanisms underlying the effects of MEG3 in ischemia still needs to be explored deeply." (PMID 29238035, 2017).
ischemia (continued). "To validate the function of GM18840, Meg3, Dnm3os, and Pvt1 in MIRI, we carried out RNA-seq analysis in an in vitro model of simulated ischemia." (PMID 34322480, 2021). "In the current study, we first determined the functional interaction among MEG3, microRNA-21 (miR-21), and programmed cell death 4 (PDCD4) in ischemia." (PMID 29238035, 2017). "In addition, MSCs from gingival tissues can reduce apoptosis through the MEG3/miR-21a-5p/PDCD4 axis, thus protecting the nerve from ischemia–reperfusion injury in the retina." (PMID 38627703, 2024). "Nevertheless, it is not clear whether MEG3 functions as a ceRNA competing for binding to miRNAs in the development of ischemia." (PMID 29238035, 2017).
lymph node metastasis (12 papers, 2017 to 2025). "Statistical analysis demonstrated that downregulation of MEG3 was correlated with lymph node metastasis, histological grade, and TNM stage and associated with poor prognosis in GBC patients." (PMID 30282996, 2018). "Because MEG3 was shown to be significantly associated with tumor size and lymph node metastasis in our previous study, we conducted receiver operating characteristic (ROC) curve analysis to test its diagnostic value." (PMID 28057015, 2017). "This meta-analysis investigated the association between MEG3 levels and distant metastasis (DM), lymph node metastasis (LNM), overall survival (OS), and recurrence-free survival (RFS) of cancer patients." (PMID 28157702, 2017). "In addition, lymph node metastasis is a key factor in treatment decisions, suggesting that plasma MEG3 methylation might use for screening high-risk patients before therapy." (PMID 28740189, 2017). "Five genes associated with lymph node metastasis (HAND2-AS1) and peritoneal and omental metastasis (KCNK15-AS1, MEG3, SEMA3B-AS1, and ZNF667-AS1) were identified." (PMID 39519394, 2024). "The low expression is related to poor prognosis, lymph node metastasis, and histological grade, suggesting that the low expression of MEG3 is related to poor prognosis in GBC patients." (PMID 34575316, 2021). "It was found that low MEG3 expression was related with lymph node metastasis, histological grade, and TNM stage in GBC patients." (PMID 30282996, 2018). "Univariate survival analysis showed that tumor size, lymph node metastasis, low MEG3 expression, and TNM stage were prognostic factors." (PMID 30282996, 2018). "We first confirmed that hypermethylation of MEG3 in plasma was a risk factor for not only CIN III, but also HR-HPV infection and lymph node metastasis." (PMID 28740189, 2017). "The results confirmed that the MEG3 expression cut-off value that we set previously for prediction of lymph node metastasis was still effective, supporting our previous results." (PMID 28057015, 2017). "The Chi-square test also indicated that MEG3 methylation was a risk factor for HR-HPV infection and lymph node metastasis." (PMID 28057015, 2017). "Meanwhile, in the including 9 studies, 5 articles performed the relationship between the expression of MEG3 and gender, 3 articles demonstrated that MEG3 were correlated with lymph node metastasis (LNM), and 3 were on distant metastasis DM." (PMID 28157702, 2017). "Then we found that MEG3 methylation in plasma was an effective biomarker for the diagnosis of CIN III (cervical intraepithelial neoplasia), HR-HPV (High risk-Human papillomavirus) infection and lymph node metastasis." (PMID 28740189, 2017). "Furthermore, HR-HPV infection and lymph node metastasis were significantly correlated with MEG3 methylation." (PMID 28057015, 2017). "In the present study, we identified MEG3 as a potential marker for lymph node metastasis." (PMID 28057015, 2017). "ROC curve analysis also revealed that MEG3 could serve as a biomarker for lymph node metastasis, with an AUC of 0.716." (PMID 28057015, 2017). "In test set, AUCs were 0.788, 0.730 and 0.804 according to MEG3 methylation of plasma for the diagnosis of CIN III, HPV infection and lymph node metastasis respectively." (PMID 28740189, 2017). "ROC curves indicated that plasma MEG3 methylation had high discriminating power to predict CIN III, HPV infection and lymph node metastasis in training set." (PMID 28740189, 2017). "In a multivariate analysis based on the Cox proportional hazards regression model, only MEG3 expression, FIGO stage, and lymph node metastasis were found to be independent prognostic markers for recurrence-free survival." (PMID 28057015, 2017). "However, there was no statistical difference in the MEG3 expression between lymph node metastasis group and non‐lymph node metastasis group as well as between well differentiation group and moderate/poor differentiation group." (PMID 31328388, 2019).
lymph node metastasis (continued). "Furthermore, we tested the predictive value of MEG3 for relevant clinical and pathological parameters, including tumor size, FIGO stage, lymph node metastasis, HR-HPV infection, age, menopause, histology, depth of invasion, differentiation, and lymphatic vascular space invasion (LVSI)." (PMID 28057015, 2017). "The MEG3 expression level was correlated with TNM staging, lymph node metastasis and tumor size but not with age, sex, extrathyroidal extension, or multicentricity of the clinical pathological characteristics examined." (PMID 31584879, 2019).
osteoarthritis (12 papers, 2015 to 2026). A noninflammatory degenerative joint disease occurring chiefly in older persons, characterized by degeneration of the articular cartilage, hypertrophy of bone at the margins and changes in the synovial membrane. "The expression of lncRNA maternally expressed gene 3 (MEG3) was decreased in patients with osteoarthritis compared with healthy cartilage samples by real-time RT-PCR." (PMID 37779916, 2023). "Hence, inhibition of MEG3 could cause osteoarthritis progression via targeting miR-16/SMAD7 axis." (PMID 37779916, 2023). "Low MEG3 expression has been found in various diseases, including cancers, osteoarthritis, and coronary artery disease." (PMID 30156956, 2019). "By contrast, MEG3 expression is downregulated in osteoarthritis patients and negatively correlates with the expression level of VEGF." (PMID 30505322, 2018). "By contrast, MEG3 expression is negatively correlated with VEGF in osteoarthritis patients, indicating its protective role in this disease." (PMID 30505322, 2018). "Methylene blue could relieve the inflammation and pain via promotion of lncRNA MEG3 in osteoarthritis." (PMID 37779916, 2023). "In addition, one report showed that lncRNA MEG3 controlled osteoarthritis progression via affecting miR-34a/Klotho axis." (PMID 37779916, 2023). "Similarly, one group also found that lncRNA MEG3 was downregulated in rat osteoarthritis cartilage tissues." (PMID 37779916, 2023). "This study indicated that lncRNA MEG3 could participate in osteoarthritis development via the modulation of angiogenesis." (PMID 37779916, 2023). "LncRNA MEG3 is critically involved in osteoarthritis development and progression." (PMID 37779916, 2023). "MEG3 accelerates osteoarthritis progression by downregulating miR-16." (PMID 37340458, 2023). "This study aimed to investigate the role of long non-coding RNA (lncRNA) maternally expressed 3 (MEG3) and related molecular mechanisms, in osteoarthritis (OA)." (PMID 31888661, 2019).
Stroke (12 papers, 2018 to 2025). Sudden impairment of blood flow to a part of the brain due to occlusion or rupture of an artery to the brain. "LncRNAs ANRIL (non-coding antisense RNA in the INK4 locus), MALAT1 (metastasis-associated lung adenocarcinoma transcript 1), MEG3 (maternally expressed 3), TUG1 (taurine upregulated 1) and ANRIL expression were significantly increased in stroke models." (PMID 35741740, 2022). "In a stroke model of transient middle cerebral artery occlusion, MEG3 was downregulated." (PMID 32241300, 2020). "Importantly, blocking MEG3 diminished infarct size and ameliorated neurological function, thereby elucidating a therapeutic strategy in stroke." (PMID 33192490, 2020). "Furthermore, lncRNA MEG3 could participate in neuronal apoptosis in stroke via sponging miR-424-5p." (PMID 38824534, 2024). "Importantly, overexpressing FTO reverses the aberrant m6A modification of MEG3 and suppresses pyroptosis, highlighting the FTO-MEG3 axis as a potential therapeutic target for stroke intervention." (PMID 41000399, 2025). "BBB disruption following stroke promotes inflammation by enabling leukocytes, T cells, and other immune cells to migrate across the BBB, which may indirectly explain the potential mechanism of the role of MEG3 in the immune microenvironment." (PMID 34220951, 2021).
chronic myeloid leukemia (11 papers, 2018 to 2023). "Recently, the long noncoding RNA (lncRNA) MEG3 in concert with a microRNA (miR-147) was reported to modulate JAK-STAT signaling in chronic myeloid leukemia (CML)." (PMID 31694222, 2019). "MEG3 decreased miR-21 levels in chronic myeloid leukemia cells." (PMID 36829176, 2023). "Moreover, in chronic myeloid leukemia blast cells, the long noncoding RNA MEG3 interacted with multiple proteins in a large complex comprising DNMT1, JAK2, TYK2, STAT3, and HDAC155." (PMID 32895373, 2020). "Furthermore, MEG3 regulated the pathogenesis of advanced chronic myeloid leukemia by targeting miR-147 through the JAK/STAT pathway." (PMID 32065781, 2020). "MEG3 regulated Imatinib resistance in chronic myeloid leukemia by inhibiting miR-21." (PMID 31660855, 2019).
colon carcinoma (11 papers, 2016 to 2024). "Anisomycin downregulates maternally expressed gene 3 (MEG3), which exhibits low levels in oral and colon cancer tissues and cells to promote proliferation by sponging miR-21-5p and miR-708-5p, respectively." (PMID 37190145, 2023). "MiR-708-5p promotes colon tumor growth in Apc(min) mice by downregulating MEG3." (PMID 37190145, 2023). "The G > A transition in the rs7158663 SNP of MEG3 is related to elevated risks of colon cancer." (PMID 35422450, 2022). "We confirmed our hypothesis using colonic crypts isolated from Apcmin mice, a typical colonic adenoma mouse model, and WT mice, showing that Meg3 accumulates to markedly lower levels in the crypts of colonic tumor samples compared to those from WT mice." (PMID 34934045, 2021). "Hence, anisomycin may inhibit oral and colon cancer cell proliferation by regulating the MEG3–miR-21-5p/miR-708-5p axis." (PMID 37190145, 2023). "Therein, four lncRNAs including CYTOR, MEG3, MIR100‐HG and MIR31HG have been previously reported to play an oncogenic role in colon cancer." (PMID 31989761, 2020). "In light of these results, we believe that MEG3 and ZEB1-AS1 play important roles in the initiation and progression of colon cancer, through their synergistic interactions with cancer-related miRNAs and finally regulating cancer-related mRNAs that were associated with cancer biological processes." (PMID 33101392, 2020). "Importantly, Meg3 acts as a ceRNA for miR-708, leading to enhanced expression of SOCS3, which in turn suppresses STAT3 signaling and malignant proliferation of colonic stem cells during the early stage of colon tumor formation." (PMID 34934045, 2021).
Hyperglycemia (11 papers, 2018 to 2025). An increased concentration of glucose in the blood. "In this study, it was observed that the pathological damage associated with hyperglycemia and suppression of lncRNA MEG3 increased the inflammatory response and decreased the expression levels of genes involved in the PI3K/AKT1 pathway." (PMID 40869265, 2025). "In the family of long non-coding RNAs, the long non-coding RNA MEG3 can reduce retinal neovascularization and prevent retinal injury from hyperglycemia." (PMID 36361470, 2022). "As additional examples, MALAT1 has been involved in increased ROS and pro-inflammatory cytokines expression, leading to endothelial damage, both at micro- and macrovascular level, while MEG3 (maternally expressed 3 lncRNA) is reduced in retina during hyperglycemia." (PMID 34299336, 2021). "They revealed that hyperglycemia promotes the expression of the MEG3 gene that could be partially responsible for endothelial dysfunction triggered by hyperglycemia." (PMID 34944571, 2021). "Meg3 overexpression inhibits TGFB1-stimulated cell proliferation and apoptosis, while hyperglycaemia stimulates TGFB1 expression." (PMID 38288471, 2023). "Additionally, MEG3 overexpression results in reduced miR-34a levels and increased SIRT1 levels in retinal cells, thereby inhibiting hyperglycemia-induced apoptosis and secretion of inflammatory cytokines." (PMID 39529988, 2024). "The authors demonstrated increased maternal placental methylation at seven CpG sites within MEG3 in women with GDM compared to women without GDM, which was correlated with maternal hyperglycemia and neonatal birthweight." (PMID 36992770, 2022).